CTLA4 (cytotoxic T-lymphocyte associated protein 4)
Diseases named in the same sentence as CTLA4 in open-access papers (continued):
Sharing a sentence is not in itself a finding about the gene and the disease.
tumor (continued). "It is also expressed at high levels on tumor-infiltrating regulatory T cells (Tregs) and antibodies targeting CTLA-4 can selectively deplete these cells by antibody-mediated cellular cytotoxicity (ADCC) mechanisms." (PMID 27660705, 2016). "The Py117 tumour curves were modelled using a repeated measures model revealing a significant difference between 12 Gy+isotype versus 12 Gy+PD-1 Ab and 12 Gy+PD-1 Ab+CTLA-4 Ab with P=0.002 and 0.0004, respectively." (PMID 28008921, 2016). "Blockade of CTLA-4 via anti- CTLA-4 antibody allows unopposed T-cell activation thereby breaking tolerance to tumor antigens." (PMID 27391442, 2016). "We chose these two genes to represent both a targetable alteration on the tumor cell (CD274) as well as a targetable indicator of a tumor immune microenvironment (CTLA4)." (PMID 27683114, 2016). "Tumor bearing mice were treated with 20Gy radiation delivered only to the tumor combined with either anti-CTLA4 antibody or anti-OX40 agonist antibody." (PMID 27281029, 2016). "CTLA-4 expression with different intensities in the tumor cell cytoplasm was observed in 186 (97.4%) patients." (PMID 26918337, 2016). "By upregulating cytotoxic T-lymphocyte-associated antigen 4 (CTLA4) and programmed cell death protein 1 (PD1), tumor cells block antitumor immune responses." (PMID 27006653, 2016). "In fact, it has been reported that MM microenvironment support overexpression of FOXP3 and CTLA4 expression in bone marrow, thus suggesting an accumulation of immunosuppressive Tregs in the tumor microenvironment of MM patients." (PMID 27493974, 2016). "Similar to CTLA-4 blockade therapy, monoclonal antibodies that block PD-1 on immune effector cells or PD-L1 on tumor cells and/or APCs have been employed to restore immune activation." (PMID 26788324, 2016). "The frequency and cytotoxic activity of CD8+ T cells are enhanced by the transient ablation of GARP+CTLA-4+ Tregs, thus attenuating tumor growth." (PMID 27095576, 2016). "Exciting data show that the tumour-mediated repression of T cell responses can be mitigated through blockade of immune checkpoint proteins, e.g., using antibodies against CTLA-4 or PD-1/PD-L1." (PMID 26751469, 2016). "The anti-tumor efficacy of MVA-BN-HER2 poxvirus-based active immunotherapy alone or in combination with CTLA-4 checkpoint blockade was investigated in a therapeutic CT26-HER-2 lung metastasis mouse model." (PMID 26961085, 2016). "In this report, the impact of combining MVA-BN-HER2 active immunotherapy and CTLA-4 blockade on efficacy was evaluated in a therapeutic mouse tumor model." (PMID 26961085, 2016). "We demonstrated a significant reduction of FOXP3+(intratumoural, stromal) and CTLA-4+T cells (stromal) in tumours following 8 cycles of NAC." (PMID 27777963, 2016). "Overall, the high ICOS+ Teff to ICOS+ Treg ratio induced by MVA-BN-HER2 alone or in combination with CTLA-4 blockade likely reflects a more effective immune response and correlated with strong anti-tumor efficacy." (PMID 26961085, 2016). "Similar to PD-1 expression, CTLA-4 was increased on all T-cell subsets (percentage of positive T cells as well as MFI) within the tumor compared with blood." (PMID 27195113, 2016). "Although immunologically purposed to regulate T cell responses for avoiding immune hyper reactivity, PD-1 and CTLA-4 expression on tumour-specific T cells abrogates anti-tumour effector functions and renders the T cells irresponsive." (PMID 27301245, 2016). "It has been documented that one of the most important tumor immune evasion mechanisms is upregulation of CTLA-4 expression on T cells with the help of TGF-β during the early stage of tumorigenesis." (PMID 27686848, 2016). "Checkpoint blockade antibodies targeting CTLA-4, PD-1, and PD-L1 axis have demonstrated impressive and durable disease control and promising responses in patients with multiple tumor types." (PMID 27234522, 2016).
tumor (continued). "Tumor samples were obtained from 158 patients with adequate clinical data for evaluation of CTLA-4 expression in tumor cells." (PMID 27050369, 2016). "Inhibition of CTLA-4 during the T-cell priming/ activation step leads to dysregulated expansion of auto-reactive T cells, including tumor-specific T-cells." (PMID 27904752, 2016). "Treg depletion at the tumor site is a requisite part of the antitumor activity of anti-CTLA-4 whose potency varies by antibody Fc isotype." (PMID 27610613, 2016). "Cytotoxic T-lymphocyte-associated protein 4 (CTLA-4) and programmed death ligand 1 (PDL-1) represent T-cell expressed checkpoint receptors extensively studied for their role in tumor immunosuppression." (PMID 28536388, 2016). "Recently it was revealed that the immune checkpoint molecules, specifically cytotoxic T-lymphocyte antigen-4 (CTLA-4) and programmed death-1 (PD-1), play an important role in tumor immune response evasion." (PMID 27686848, 2016). "Tumor-bearing mice were treated with different combinations of immunomodulatory antibodies (α-CTLA-4, α-PD-1, α-CD137) or interleukin-2 (IL-2) alone or in combination with SBRT." (PMID 27160390, 2016). "These antibodies have been shown to improve anti-tumor T cell responses in preclinical and early clinical studies and can enhance the efficacy of α-PD-1 and α-CTLA-4 therapy." (PMID 27160390, 2016). "A single dose of DC vaccine/anti-CTLA-4 inhibits tumour growth in 60% of the challenged mice with EL4 lymphoma cells; moreover the vaccine or CTL-4 blockage administrated alone has no potent antitumour effect." (PMID 27212807, 2016). "When anti-CSF1 treatment was combined with anti-PD-1/anti-CTLA4 immunotherapy with gemcitabine chemotherapy they observed complete tumor regression in 30% of mice and an average tumor regression of 85%." (PMID 27886105, 2016). "The combination of anti-CTLA-4 antibodies and anti-4-1BB has demonstrated preclinical success in multiple tumor histologies." (PMID 27034234, 2016). "Recent success of antibodies targeting inhibitory immune checkpoints such as CTLA-4 and PD-1 has again shifted the focus on inhibitory molecules in immune cell signalling for a beneficial anti-tumor response." (PMID 27340370, 2016). "At this time there are no inhibitors of HHLA2 available for clinical use, but preventing immune tolerance, by targeting PD-L1 or CTLA-4, in the tumor microenvironment has proven effective in a variety of other cancers." (PMID 27531281, 2016). "Antibodies to CTLA-4 and anti-PD-1 showed enhanced antitumor activities when used in combination in two mouse syngeneic tumor models." (PMID 27610613, 2016). "The recent successes of checkpoint inhibitors, specifically anti-PD1 and anti-CTLA4 with others under development, have prompted us to turn our attention to effective vaccine strategies, which induce tumor-specific T cell activation." (PMID 27367740, 2016). "After controlling for age and clinical stage, multivariate analysis (Cox) found that tumor CTLA-4 expression was an independent predictor of shorter OS (HR 2.016, P = 0.004)." (PMID 27050369, 2016). "The median tumor CTLA-4 score was 2, the median lymphocyte CTLA-4 score was 0.7, the median tumor CD28 score was 1, and the median lymphocyte CD28 score was 0.7." (PMID 26918337, 2016). "Such antibodies improve T cell function by blocking CTLA-4 or PD-1/PD-L1 signaling which releases the anergic T cells to become active participants in the anti-tumor immune response." (PMID 27687804, 2016). "Here, combining detailed analysis of human tumour samples with preclinical tumour models, we report that concomitant blockade of CTLA-4 and PD-1 improves anti-tumour immune responses and synergistically eradicates tumour." (PMID 27498556, 2016). "We began preclinical assessment of anti-CTLA-4 and anti-PD-1 combination therapy in mouse syngeneic tumor models." (PMID 27610613, 2016).
tumor (continued). "Recently, a study illustrated that anti-CTLA-4 antibody depleted Treg in tumor lesions through Fc-dependent mechanism to potentially enhance antitumor immunity in mice." (PMID 26788324, 2016). "Tumor-infiltrating Tregs highly upregulate expression of various immune checkpoint molecules (CTLA-4, PD-1, LAG-3, TIM-3, GITR), making them viable targets for ICI." (PMID 27509527, 2016). "AH1-specific CD8+ T cells were also expanded in the spleens of CT26 tumor-bearing mice treated with anti-PD-1 and anti-CTLA-4, increasing from approximately 1% to an average of 15.6% of splenic CD8+ T cells (p<0.001)." (PMID 27610613, 2016). "Tumor CTLA-4 expression was a significant prognostic factor for D-FFS (p = 0.044), and the UICC and CRP level were also significant prognostic factors (p < 0.001 and p = 0.005, respectively)." (PMID 26918337, 2016). "Combination of GVAX (irradiated tumor cell expressing GM-CSF) with anti-CTLA-4 and anti-PD-1 checkpoint blockade was very promising in preclinical studies, leading to the first clinical trials of checkpoint blockade in patients with cancer." (PMID 27660710, 2016). "Monoclonal antibodies interrupting immune checkpoints, such as anti-CTLA-4, anti-PD-1, and anti-PD-L1 can unleash anti-tumor immunity and mediate durable cancer regressions." (PMID 27588404, 2016). "In contrast to CTLA-4, it is viewed that PD-1/PD-L1 pathway acts to restrain T cell responses in the peripheral tissues, such as at the tumor bed where ligand and receptor are both in abundance." (PMID 28031817, 2016). "In the present study, the co-expression of CD28 and CTLA-4 on both tumor cells and tumor-infiltrating lymphocytes (TILs) was detected." (PMID 26918337, 2016). "All patients had received prior anti-CTLA-4 therapy and a BRAF inhibitor if a V600 mutation was present in their tumor." (PMID 26767073, 2016). "When α-PD-1 was added to α-CTLA-4 blockade as in the combination group, ‘escape' of tumour from α-CTLA-4 monotherapy was blocked and all tumours were rejected, providing direct evidence that MB49 tumours utilize the PD-1 pathway to evade α-CTLA-4 monotherapy." (PMID 27498556, 2016). "We found that combining the poxvirus-based active immunotherapy with CTLA-4 checkpoint blockade strongly synergized to increase overall survival in a therapeutic mouse tumor model." (PMID 26961085, 2016). "Considering the much higher aggressiveness of the lung metastasis tumour model, the dose of anti-CTLA-4 antibody used here was doubled." (PMID 27767031, 2016). "To understand how anti-CTLA4 pretreatment enhances tumor control by radiation therapy, we investigated the mechanism of action of this checkpoint inhibitor." (PMID 27281029, 2016). "If Treg function can be suppressed through CTLA-4 blockade with an agent such as ipi, then an immune response to tumor antigens can potentially emerge and expand." (PMID 27330811, 2016). "Pre-clinical murine models have shown that, in conjunction with activating Teff and CTLs, anti-CTLA-4 mAbs exert anti-tumor activity via antibody-dependent cell-mediated cytotoxicity (ADCC)-mediated depletion of intra-tumoral Tregs." (PMID 27509527, 2016). "The cytotoxic T-lymphocyte antigen (CTLA) 4 was also required for the injection of anti-CTLA-4 antibodies into tumor-bearing mice leading to blockade of tumor growth." (PMID 27868073, 2016). "Preclinical studies in solid tumor models demonstrated regression of established tumors and the rejection of further tumor challenge following anti-CTLA-4 mAb treatment." (PMID 31093342, 2016). "Further prospective validation is warranted to characterize the tumor antigen specific antibody response as potential biomarker for anti-CTLA-4 therapy." (PMID 26788324, 2016). "The 3-year FFS in the low tumor CTLA-4 expression group was also higher than that in the high tumor CTLA-4 expression group (82.8% vs. 68.0%, p = 0.009)." (PMID 26918337, 2016).
tumor (continued). "CTLA-4 blockade has also been shown to actually potentiate a robust spectrum of tumor specific antibody responses." (PMID 26788324, 2016). "Increased mRNA levels of CTLA-4 were shown to be associated with ALN metastases and more advanced tumour stage." (PMID 27777963, 2016). "This is in accord with previous studies, which have shown an increase in functional Treg in concert with a much greater increase in active Th following administration of an anti-CTLA-4 antibody, leading to the observed anti-tumor effect." (PMID 27330811, 2016). "Anti-TIM-3 mAbs have been shown to modestly inhibit solid tumor growth in murine models, and have induced more impressive control of tumor growth in combination with CTLA-4 and PD-1 targeting therapies." (PMID 31093342, 2016). "Another immunotherapeutic strategy, the blocking of CTLA-4 with ipilimumab led to enhanced T cell activation and increased tumor rejection and resulted in long-term tumor control in about 20 % of patients." (PMID 27075584, 2016). "The two most advanced tumor immunotherapy antagonists target CTLA-4 and PD-1, which promote negative regulation through distinct but complementary signaling pathways in Teffs." (PMID 27610613, 2016). "We evidence a functional recovery of T cell responsiveness to polyclonal stimuli and expansion of TAAs specific CD8+ T cells using peptide pulsed DCs, with an increase of CTLA-4 and memory effector phenotype after anti-tumor therapy." (PMID 27484900, 2016). "The group with a significant contralateral tumour response compared to the RT and PD-1 Ab treated mice was the combination of 20 Gy+PD-1 Ab+3 days pre-CTLA-4 Ab treatment." (PMID 28008921, 2016). "This promotes ADCC-mediated Treg depletion and re-establishment of an anti-tumor immune response following CTLA-4 blockade." (PMID 27509527, 2016). "The 3-year OS in the low tumor CTLA-4 expression group was higher than that in the high tumor CTLA-4 expression group (91.4% vs. 81.2%, p = 0.043)." (PMID 26918337, 2016). "Tumor-bearing mice that received anti-CTLA4 on day 7 prior to radiation cleared their tumors with an undefined median survival (p = 0.002 vs radiation alone)." (PMID 27281029, 2016). "The observation of the expression of various inhibitory receptors and ligands on immune cells and tumor cells lead to the development of checkpoint blockade antibodies, such as the anti-PD-1 antibody and the anti-CTLA-4 antibody." (PMID 27854240, 2016). "When the CTLA-4 score of the tumor was 2 or higher, patients were considered to have high expression (present in 98 of 191 patients)." (PMID 26918337, 2016). "In contrast, CTLA-4 blockade beginning 4 days after VV injection potentiated VV anti-cancer efficacy, leading to a significant synergistic reduction in tumour growth compared with monotherapy." (PMID 26751469, 2016). "In summary, we showed that combination of poxvirus-based active immunotherapy with CTLA-4 blockade resulted in synergistic anti-tumor efficacy." (PMID 26961085, 2016). "On the other hand, e.g., anti-CTLA-4-mediated immune responses were only observed when combined with fractionated RT (5 × 6 Gy) in murine tumor models." (PMID 28066420, 2016). "Immune checkpoint inhibition directed against PD-1 and CTLA-4 has the potential to activate effector T-cells against a wide spectrum of tumor- and self-antigens." (PMID 26981243, 2016). "For example, tumor cells are believed to promote the expression of CTLA-4, which is a molecule expressed by T cells that competes with CD28 for the co-stimulatory molecule CD80 (B7.1), thereby suppressing T cell activation." (PMID 27092248, 2016). "These engineered DCs have the ability to not only present the tumor antigen of interest but also secrete anti-CTLA4 and anti-GITR, thus locally modulating immune checkpoints and the tumor microenvironment." (PMID 26665011, 2015).
tumor (continued). "Antagonistic anti-CTLA4 antibodies have been extensively tested in cancer models as a strategy to activate anti-tumor immunity, and CTLA4 was the first immune checkpoint targeted in the clinic for cancer therapy." (PMID 25614821, 2015). "In the immunosuppressive tumor microenvironment, blocking CTLA-4 has the potential to directly activate CD4+ and CD8+ effector T cells, leading to tumor clearance." (PMID 25806106, 2015). "Targeted blockade of CTLA-4 or PD-1 with antagonist monoclonal antibodies (mAbs) releases the “brakes” on T cells to boost anti-tumor immunity." (PMID 25763356, 2015). "Observations made to date suggest that anti-CTLA-4 antibodies function not only by blocking inhibitory signals from reaching effector T cells but also by depleting the T reg cells present in the tumor microenvironment." (PMID 26579545, 2015). "In a seminal study, administration of anti-CTLA-4 mAb resulted in the rejection of pre-established tumors, as well as subsequent immunity to tumor rechallenge, in a murine model." (PMID 26082780, 2015). "Blocking CTLA-4 thereby allows CD-28 to interact with B7-1 and B7-2, enhancing the body's cellular immune response and ability to eradicate tumor cells." (PMID 29546098, 2015). "A limited proportion of patients receiving CTLA-4-blocking drugs achieve the objective tumor response, while most have irAEs." (PMID 26337719, 2015). "Recently, investigators have focused on harnessing the power of checkpoint inhibitors, such as CTLA-4 and PD-1, to release the “brakes” on an anti-tumor T cell response through antibody-mediated antagonism of these receptors." (PMID 25763356, 2015). "Many tumours turn off T cells specific for tumour antigens by binding to ‘check-point’ receptors such as PD-1 or CTLA4, and new treatments that block these receptor–ligand interactions have great therapeutic potential." (PMID 26702035, 2015). "Depletion of Tregs and anti-CTLA-4 mAb treatment are effective and promising anti-tumor immunotherapies." (PMID 25851535, 2015). "Univariate analysis (log-rank) associated higher density of interstitial CTLA-4+ lymphocytes with longer DFS and OS, but higher tumor CTLA-4 expression with shorter OS." (PMID 25893809, 2015). "The combination of anti-CTLA-4 immunotherapy with agents that prime immune response is illustrated in multiple tumor models and highlights the importance of immune priming for successful anti-CTLA-4 immunotherapy." (PMID 26079374, 2015). "Recent research has emphasized the importance of individually mutated tumor antigens in antitumor immune responses mediating tumor rejection, especially in the context of monoclonal antibody therapies blocking immune “checkpoints” such as CTLA-4 and PD-1." (PMID 26143264, 2015). "Consecutive 3 doses of radiation resulted in tumor growth delay and the effect was enhanced significantly by addition of CTLA-4 blockade." (PMID 25980578, 2015). "Promising immunotherapeutics for HCC include oncolytic viruses, CTLA-4 blockade, and tumor-antigen specific antibodies." (PMID 28943622, 2015). "IL-2 either as a monotherapy or in combination with CTLA-4 blockade increased the proportion of less fully differentiated (CD27-CD11b-) NK cells as compared with the exhausted (CD11b+) NK cells within the tumor observed with CTLA-4 blockade alone." (PMID 25992289, 2015). "Analogous to CTLA-4 and PD-1, the immunologic dampening triggered by adenosine at sites of inflammation is mirrored by its effect in the tumor microenvironment." (PMID 25941561, 2015). "Although this study failed to associate tumor CTLA-4 expression with density of interstitial CTLA-4+ lymphocytes, the prognostic value of interstitial CTLA-4+ lymphocytes density was affected by CTLA-4 expression in tumor cells." (PMID 25893809, 2015).